TNF (tumor necrosis factor)
Diseases named in the same sentence as TNF in open-access papers (continued):
Sharing a sentence is not in itself a finding about the gene and the disease.
tumor (continued). "M1 macrophages are conventionally activated macrophages that secrete pro-inflammatory cytokines such as IL-1β, IL-6, IL-8, IL-18, TNF-α, and IFN-γ, and exert an anti-tumor effect." (PMID 32993787, 2020). "It is known that γδ T cells exert anti-tumor activity by generating various cytokines, such as IFN-γ and TNF-α." (PMID 31947966, 2020). "We compared the methylation status of the NT5E gene according to the expression of inflammatory markers including TNF-α, IL-4, NF-κB p50, CD4+, and CD8+ T cells, CD68+ macrophages, intratumoral and peritumoral inflammation in tumor tissues." (PMID 33198064, 2020). "We also found that in the combination PD-1 antibody and evodiamine treatment group, tumor-infiltrating CD8+ T cells showed stronger activation phenotypes and more increased IFN-γ, TNFα and Granzyme B (GrzmB) production." (PMID 33208183, 2020). "Tumor cells-macrophage co-culture increases expression of IL10, IL12, IL6, TNF, CCL5, CCL22, and CSF1 in macrophages, thereby inducing M2-like polarization." (PMID 32219066, 2020). "STING can induce the expression of IFNβ, TNFα, or both, the latter seems to be the case in B16F10 tumor cell response to radiation." (PMID 33202881, 2020). "It develops in response to tumor-derived factors and releases IL10, IL12, TNFα, TNFβ, VEGF, CCL20, CCL22, and MMP9, thereby supporting tumor growth and metastases and acting as an immunosuppressant." (PMID 32900001, 2020). "In this setting, M2-derived TGF-β decreased tumor infiltrating NK expression of Ki-67 as well as secretion of IFN-γ and TNF-α." (PMID 32612950, 2020). "Despite the lower magnitude of anti-tumor activity seen in vitro when IFN-γ was the only Th1 cytokine, for the in vivo study, we chose to omit TNF-α, due to its reputation of unacceptably high toxicity when administered systemically." (PMID 32041347, 2020). "In this study, in the orthotopic-mice model of HCC, YPF increased the levels of Th1 cytokines (IL-2, IL-12, TNF-α, and IFN-γ), decreased the levels of Th2 cytokines (IL-4, IL-5, IL-10, and IL-13), and increased the Th1/Th2 ratio in tumor and adjacent tissues." (PMID 32351590, 2020). "In contrast, CD200 overexpression in CD200 transgenic mice was found to increase tumor-induced IFN-γ and decrease inflammatory cytokine, TNF-α, and IL-6 expression." (PMID 32635224, 2020). "TNF-α, IFN-γ and GM-CSF are known to be involved in mechanisms such as induction of tumor cell apoptosis as well as proliferation and activation of T-cells." (PMID 32370811, 2020). "Mice immunised with (MS@OVAinMOF)@(anti-CTLA4inMOF) show the highest population of tetramer+CD8+ T cells in the spleen and tumour sites and the highest cytokine contents in the spleen (IFN-γ and TNF-α) among all the groups." (PMID 32737343, 2020). "IL-2 can regulate the cellular activity of leukocytes in the immune system, react with antibodies, hematopoiesis and tumor surveillance, and induce killer cells to produce cytokines such as IFN-γ and TNF-α." (PMID 32425919, 2020). "We compared normal and tumor tissues for MK2 downstream cytokine production and also found a significant increase in IL-1β, IL-6, and TNF-α in tumors with lymph node metastasis compared to non-metastatic tumors." (PMID 32216812, 2020). "In fact, the activation of NF-kB leads to the release of IL-6, IL-12, IL-17 and IL-18 as well as the tumor necrosis factor alpha (TNF-alpha), triggering persistent inflammation in the tumor microenvironment." (PMID 32878124, 2020). "Intratumoral injection of cGAMP transiently induced migration of macrophages into tumor site in a STING-dependent manner and these cells exhibit phagocytosis and tumor necrosis factor α (TNFα) production." (PMID 32000794, 2020). "Quantification of CD8 TIL functional capacity from CON NT, CON + anti-PD-1, ACA NT, and ACA + anti-PD-1 revealed respective stepwise increases in the frequencies of IFNγ+ TNFα+, and perforin+ CD8 T cells within the tumor microenvironment." (PMID 33036247, 2020).
tumor (continued). "We observed a 5–7- fold increase in the frequency of tumor antigen specific CD8 T cells expressing IFNγ and TNFα in FOLFOX-treated tumors compared to controls." (PMID 32391270, 2020). "It was also shown that specific antibodies against cytokines TNFα, IFNγ and IL-2, which were co-incubated with Tag7-PBMC, decrease the cytotoxic effect of Tag7-PBMC against tumor cells." (PMID 33291689, 2020). "It was observed that tea polyphenols (0.1% in water for 42 days) inhibited the formation of tumor through down-regulating the expression of COX-2, TNF-α, IL-6, β-catenin, and C-myc and up-regulating the expression of IL-4 and IL-10." (PMID 32410986, 2020). "High plasma levels of IL-6, TNF-α, INF-γ, and IL-1β have been observed in both tumor-bearing animals and cachectic cancer patients." (PMID 31941005, 2020). "NK cells secrete tumor necrosis factor (TNF) and interferon (IFN), which exert a killing effect on cells, as well as having an important role in anti-tumor innate immunity." (PMID 32214002, 2020). "Chronic inflammation in the tumor microenvironment is induced by overexpression of pro-inflammatory cytokines, including CSF-1, VEGF, TGF-β, and tumor necrosis factor α (TNF-α)." (PMID 33329549, 2020). "TNFα stimulates the secretion of MMPs in epithelial tumors and enhances EMT to promote invasion and migration of tumor cells." (PMID 33339340, 2020). "Studies show that TNFα promotes activation-induced cell death (AICD) of CD8+ T lymphocytes through TNFR2 signaling and that it prevents them from infiltrating the tumor bed." (PMID 32391269, 2020). "Recent studies have reported that elevation of TNF-α and IL-2 in tissues by transfecting oncolytic adenovirus loaded with TNF-α and IL-2 sequence into T cells modulates host tumor immune status and orchestrates TAMs toward the M1 type." (PMID 33505964, 2020). "Upon tumor recognition through the T-cell receptor (TCR), NK-receptors, or NKG2D, γδ T cells generate the pro-inflammatory cytokines TNF-α and IFN-γ, or granzymes and perforin that mediate cellular apoptosis." (PMID 31947966, 2020). "The increased levels of adipose tissue-derived factors, such as TNF-α, IL-6, IL-8, macrophage chemoattractant protein (MCP-1), and leptin, and their role in tumor progression have been well-documented." (PMID 32847136, 2020). "So called M1 macrophages are induced by lipopolysaccharide (LPS) and type 1 cytokines (mainly IFN-γ), express high levels of tumor necrosis factor (TNF), IL-12, iNOS, and MHC class II molecules and are considered to participate in anti-tumor immunity." (PMID 32499785, 2020). "Administration of anti-TGF-3 also enhanced both the systemic and tumor-infiltrating E7-specific CD8+ T cell response in mice treated with cisplatin and E7 long peptide, while administration of anti-TNF-a suppressed the generation of such immune responses." (PMID 32111835, 2020). "According to multiple studies, trans-presentation of TNF, BAT3, NKG2D, IL-15Rα, and rhIL-15 in DCs-derived EVs were found to be the mechanism involved in NK cells’ ability to inhibit tumor growth." (PMID 33628730, 2020). "In a similar study, APS upregulated the expression of TNF-α, IL12, and IL2, whereas it decreased the levels of IL10 and downregulated the expression of multidrug resistance 1 mRNA and P-glycoprotein in H22 tumor-bearing mice." (PMID 32265719, 2020). "Since the tissue microenvironment and accompanying factors that affect Tregs can vary widely between tumor types in mice and men, it will be important to understand the precise conditions that modulate the effects of IFN-γ and TNF-α on intratumoral Tregs." (PMID 32005826, 2020). "These cancer cells transfer cGAMP—produced by cGAS in response to tumor cytosolic DNA—to astrocytes by establishing gap junctions, thereby activating STING and inducing type I IFN and TNFα expression." (PMID 32774773, 2020).
tumor (continued). "Thereafter, activated CTLs recognize tumor cells and induce tumor regression by secreting cytokines, including interferon-γ (IFN-γ), tumor necrosis factor-α and interleukin-6." (PMID 32317755, 2020). "On the other hand, TNFα also upregulates pro-metastatic factors, such as MMPs and MUC4, and enhances tumor dissemination." (PMID 32391269, 2020). "Cytotoxicity against CD155 positive tumor cells was enhanced with an increased level of cytokines, such as IFN-γ, IL-6, and TNF-α." (PMID 32882824, 2020). "Pro-inflammatory cytokines released after surgery, such as TNF-α and transforming growth factor-beta (TGF-β), have also been shown to stimulate tumour cell adhesion." (PMID 32357913, 2020). "mRNA levels of inflammatory cytokines in tumor tissue of irradiated mice were also modulated by DEX, showing a pronounced decrease for IL-6 and TNFα." (PMID 32325715, 2020). "Secretion of interferon γ (IFN-γ) and tumor necrosis factor α (TNF-α) was shown to increase IDO expression in various types of myeloid cells, including monocytes/macrophages, neutrophils, dendritic cells as well as tumor cells." (PMID 32107566, 2020). "TNF also triggers the activation-induced cell death of CD8 T lymphocytes and impairs tumor infiltration by CD8 T lymphocytes." (PMID 33381115, 2020). "Tumor necrosis factor (TNF) is a well-studied inflammatory cytokine and can promote or block tumor progression." (PMID 33003572, 2020). "Upregulated serum IL-2 and TNF-α levels and increased CD69 expression on the surface of tumor cells were also observed, which correlated with enhanced adaptive immunity." (PMID 32595757, 2020). "C-PC/CMC-CD55sp nanospheres played an important role in tumor suppression, reduced the expression TGF-β, and increased IL-6 and TNF-α." (PMID 32636744, 2020). "TAMs are derived from monocytes attracted in the tumor microenvironment (TME) (via CCL2, CCL8) and are differentiated trough IL-4, IL-10, IL-13 and TNF-α stimuli." (PMID 32344813, 2020). "Th1 lymphocytes exert an antitumor effect by releasing tumor necrosis factor α (TNF-α), and IFN-γ, while Th2 cells mainly produce interleukin (IL) 4 (IL-4) and thereby promote tumor growth by inhibiting the host’s immune system." (PMID 33050416, 2020). "FAP-α expressing cells are a significant immunosuppressive component that can result in the hypoxic necrosis of tumor and stroma cells through a process involving IFN-γ and TNF-α." (PMID 33634030, 2020). "During brain metastasis, cGAMP transferred to bystander cells (e.g., astrocytes) can also produce IFNα and TNFα in the TME but, in this context, it will support tumor development and chemoresistance." (PMID 32411126, 2020). "In fact, neutrophils extravasate the blood and recruit into tumor tissue in response to cytokines (IFN-γ and TNF-α), chemokines (KC/CXCL1 and MIP2α/CXCL2 in mice) and cell adhesion molecules (i.e., CD11b)." (PMID 32499786, 2020). "Tumor-infiltrating T, B, and NK cell levels and plasma concentrations of Th1 (IL-2, IFN-γ, and TNF-α), Th2 (IL-4, IL-5, IL-6, and IL-10), Th9 (IL-9), and Th17 (IL-17A, IL-17F, IL-21, and IL-22) cytokines were evaluated." (PMID 32802733, 2020). "CAR T cells secrete inflammatory cytokines only following tumour antigen recognition through the CAR, which avoids the potential detrimental effect of systemic TNF secretion." (PMID 31947615, 2020). "Vaccination with Photofrin-PDT treated tumor cells induces DC maturation, increases IFN-γ and TNF-α secretion by splenocytes, as well as their cytolytic activity, and is effective against poorly immunogenic tumors." (PMID 31991650, 2020). "To further support the notion that the CD163-labelled M2 macrophages were activated, we showed expression of IL-10, TNF-α, TGF-β1 and IL-6 in all tumour tissues." (PMID 32070062, 2020). "It modulates tumor necrosis factor-alpha (TNF-α) signalling through direct and indirect effects on the tumor microenvironment." (PMID 32508920, 2020).
tumor (continued). "The immune cell subpopulation infiltrated into the tumor mass as well as the expression of interferon-gamma (IFN-γ) and tumor necrosis factor-alpha (TNF-α) in T cells was assessed by flow cytometry and/or immunohistochemistry." (PMID 33020243, 2020). "Interestingly, by using an anti-PD-1 antibody or a recombinant PD-L1 molecule, the production of IFN-γ and TNF-α was inhibited, suggesting that, in the tumor microenvironment, the anti-tumor activity of ILC3s could be repressed because of their PD-1 expression." (PMID 33255582, 2020). "In particular, TAMs contribute to tumor initiation by secreting pro-tumorigenic signaling molecules, including TGF-β, TNF-α, ILs, M-CSF and CXCLs." (PMID 33212945, 2020). "In this study, immunohistochemical expression of TNF-α, IL-6, IL-1β, and IL-2 in GEP-NENs was evaluated and correlated with the proliferation, tumor grade, tumor, node, metastasis (TNM), and outcomes." (PMID 32156252, 2020). "M2-like TAMs contribute to tumor angiogenesis by secreting soluble factors inducing endothelial cell proliferation, including VEGF-A, interleukin (IL)-1β, IL-6, tumor necrosis factor (TNF)α, CXCL8, and fibroblast growth factor (FGF)-2." (PMID 32878276, 2020). "A variety of cytokines released by MCs including IL-1, IL-4, IL-8, IL-6, MCP-3, MCP-4, TNF-α, IFN-γ, LTB4, TGF-β, and chymase contribute to developing inflammation, inhibiting tumor cell growth, and inducing tumor cell apoptosis." (PMID 31256327, 2020). "TNF-α - TNFR1 axis induce apoptosis whereas, signalling through the second pathway (TNFR2) promote the proliferation of tumour cells and suppressive immune cells." (PMID 31076897, 2020). "We found that these receptors are highly correlated to the innate and adaptive immunity-related cells, as well as IL-10, IL-6, CXCL10, CCL2-CCL5, TGFB1 in KIRC tumors, whereas in KIPRP tumor tissues IL8, IL1A, and TNF were highly correlated." (PMID 33330620, 2020). "Among others, these tumor and stroma-derived growth factors and cytokines include interleukines (IL), chemokines (CXC), tumor necrosis factor-alpha (TNF), epidermal growth factor (EGF), vascular endothelial growth factor, and fibroblast growth factor (FGF)." (PMID 32660072, 2020). "TNF-α and IL6 are important pro-inflammatory cytokines known to have pleotropic function in immune response, inflammation, cell death and tumor progression." (PMID 33123499, 2020). "Lastly, after the purified tumour-infiltrating PMN-MDSCs were cultured for 24 h in vitro, cells from the HSD group expressed more TNF-α and ICAM-1 and less prostaglandin E2 (PGE2), Arg1, CCL2 and CCL5 than those from the NSD group." (PMID 32265505, 2020). "Colloidal gold-based nanoparticles have been designed to target the delivery of tumor necrosis factor (TNF) and paclitaxel to solid tumors, introducing AuNPs as tumor-targeted drug delivery vectors." (PMID 32806755, 2020). "Currently TNF, WNT10A, PDGFA, and NRG1 secreted by infiltrated dendritic cells in the tumor microenvironment were identified to be likely involved in the neuropathic pain using RNA-seq, scRNA-seq, and ChIP-seq data." (PMID 32434423, 2020). "Collectively, these data support the tumor suppressive role of PPARγ in GBM by suppressing stemness and attenuating TNFα-induced PMT." (PMID 32280134, 2020). "Only SFV4-infected tumor cells consistently induced DCs to secrete Th1 cytokines (IFN-γ, IL-12, TNF-α), Th2 cytokines (IL-4, IL-13), proinflammatory cytokines (IL-6, IL-8, IL-1β,) and anti-inflammatory cytokine (IL-10)." (PMID 31969562, 2020). "K46E mice responded to GL261 tumor with increased CD8+ T cell infiltrates that expresses elevated levels of IFN-γ and TNF-α." (PMID 32896273, 2020).
tumor (continued). "The increased expression of numerous proinflammatory cytokines, including IL6 and TNFα and chemokines involved in immune cell chemotaxis observed via bulk RNA sequencing, could support trafficking and maturation of various immune cell populations to and from the tumor tissue." (PMID 32754281, 2020). "Mechanistic studies revealed that expression of various factors such as caspase-8, TNFα, RIP1, c-FLIP, FADD, cIAP1/2, and XIAP is essential for SM-mediated tumor cell death." (PMID 32325691, 2020). "We also demonstrate that pemetrexed can synergize with PD-1/PD-L1 blockade to enhance the production of IL-2, TNF-α and IFN-γ within the tumor microenvironment in the mouse syngeneic models." (PMID 33243934, 2020). "We applied the AcTakine concept to both mouse and human TNF, resulting in AFRs with a targeting efficiency exceeding 100‐fold, and targeted them to CD13 expressed on endothelial cells of the tumor neovasculature." (PMID 31912630, 2020). "For example, IL-15-stimulated ILC1s promote tumor cell lysis via the production of IFN-γ and TNF-α, with the consequent upregulation of MHC-I expression, whereas IL-12-activated ILC1s have complete functional impairment and promote tumorigenesis." (PMID 32867025, 2020). "Third, circulating lymphocytes have anti-tumor effects by secreting cytokines, including interferon (IFN)-γ and tumor necrosis factor (TNF)-α, and promoting cytotoxic cell death." (PMID 32913461, 2020). "TAMs are recruited to the tumor site through tumor secretion of cytokines and chemokines, including ATP, CSF-1, CCL2, GDNF, GM-CSF HGF/SF, MCF-3, SDF-1, TNF and VEGF6,15." (PMID 32555306, 2020). "Briefly, our first proposal would be extracting naïve T lymphocytes and tumor cells from the patient, and co-cultivate them in the presence of cytokines to activate cytotoxic T-cell response: i.e., IL-2, INF-α and γ, and TNF-α." (PMID 33276556, 2020). "Expression of chemokine receptors on MSC membrane (e.g., chemokine receptor 4) is influenced by the features of tumor microenvironment (hypoxia and TNF-α), which makes such cytokine/receptor pair reactions more specific for MSC migration to the tumor site." (PMID 32793565, 2020). "It has the ability to produce the cytokines with anti‐tumour effect as IFN‐γ and TNF‐α against cancer cells via stimulating macrophages and DCs and recognize the antigens of tumour cells without major histocompatibility complex restriction." (PMID 32643277, 2020). "Classically activated macrophages (M1) protect the body from external pathogens and destroy tumor cells by secreting the pro-inflammatory cytokines IL6, IL12, IL23, and tumor necrosis factor-α (TNF-α), as well as releasing reactive oxygen/nitrogen species." (PMID 32582698, 2020). "Concentrations of tumor-promoting cytokines, including IL-6, VEGF, TGF-β, and TNF-α were determined in the serum of NSCLC patients and controls using ELISA." (PMID 33125430, 2020). "Lately, several studies have shown the prometastatic role of TNFα and its participation in the epithelial-to-mesenchymal (EMT) process necessary for migration of tumor cells to establish metastasis." (PMID 32391269, 2020). "The concentration of TNF-α and immunoglobulin-like cell adhesion molecules like ICAM-1 and VCAM-1 will trigger the chemotaxis which is directly related to the metastasis of tumor cells by vascular penetration." (PMID 32764400, 2020). "As expected, DCs responded to bacteria treated tumor cells with significant increase in cytokines secretion, including IL-1β, IL-6, MCP-1, and TNF-α." (PMID 33643911, 2020). "Then we isolated NF-κB1+ cells from these two xenograft models and sorted them into endothelial cells, immune cells and tumor cells, and researched the expression profile of the upstream of NF-κB1: TNF-α (tumor necrosis factor-alpha)." (PMID 31829270, 2019).